JAK3 (Janus kinase 3)
Diseases named in the same sentence as JAK3 in open-access papers (continued):
Sharing a sentence is not in itself a finding about the gene and the disease.
venous thromboembolism (1 paper, 2023). Occlusion of the lumen of a vein by a thrombus that has migrated from a distal site via the blood stream. "Even prior to the ORAL Surveillance, concerning safety signals appeared during the trials of BARI regarding increased risk of venous thromboembolism (VTE) suggesting a possible class effect of JAK inhibitors, rather than a risk associated solely with TOFA and strong JAK1/JAK3 inhibition." (PMID 37892827, 2023).
WHIM syndrome (1 paper, 2022). "Innate immune cells (e.g., NK cells and neutrophils), which play a role in elimination of virus infection response, are affected in LAD1 deficiency, IL2RG/JAK3 deficiency, and WHIM syndrome." (PMID 35665206, 2022).
ZIKV infection (1 paper, 2020). "Interestingly, immune escape by ZIKV infection could be caused by downregulation of prolactin signaling including IRS2, PIK3C3, JAK3, STAT3, and IRF1 as well as mitochondria dysfunction and oxidative phosphorylation in myeloid dendritic cells." (PMID 32287277, 2020).
tumor (137 papers, 2009 to 2026). "Searching the genomic database revealed another entry for the same mutation: a 40-year-old patient with T-ALL positive for JAK3 p.Q988P was detected as a somatic variant of uncertain clinical significance in a tumor sample obtained before chemotherapy." (PMID 41009670, 2025). "Other mutations of note include JAK3 (10% patient tumours, 25% cell lines, 33% PDX models) and NF1 (10% patient tumours, 0% cell lines, 25% PDX models)." (PMID 40415599, 2025). "Hyper-activation of the JAK3-STAT signaling pathway has been linked to tumor development and progression by inducing factors associated with suppressive immune cell recruitment, angiogenesis and neo-vascularization." (PMID 38149248, 2023). "Alterations of the JAK/STAT pathway, especially JAK3, involving its mutations and aberrant phosphorylation are highly prevalent and relate to tumor cell survival." (PMID 37529691, 2023). "Both of these T−B+NK− SCID models exhibited perturbed immunity, with the il2rga mutants displaying dysregulated intestinal microbiota and defective tumor immunity and the jak3 mutants being susceptible to the development of lymphoid malignancy." (PMID 37047441, 2023). "Several of the most highly induced genes, CHI3L1, GPX1, PLIN1, PLIN4, and JAK3, have been linked to enhanced growth or cell survival in other tumor types." (PMID 35787784, 2022). "Mutations in the Jak-STAT pathway have shown evidence in contributing to EITL with Jak3 mutations accounting for 2 out of 4 tumor samples (alterations occurring in 2 distinct activating positions: V674A and M411I)." (PMID 33814980, 2021). "In conclusion, we established nude mice with complete loss of NK cells, BALB/c Jak3 deficient (Nude-J) mice, and showed that NK cells play a crucial role in the rejection of human tumor cells." (PMID 33906298, 2021). "A selective JAK3 inhibitor PRN37 has been shown to cause more tumor growth inhibition than tofacitinib in an ENKTL JAK3 mutated xenograft model." (PMID 32098335, 2020). "A selective inhibitor of JAK3 (PRN371) has recently been demonstrated to have a more potent anti-tumor activity than tofacitinib in a xenograft model of ENKTL with a JAK3 mutation." (PMID 30935402, 2019). "Furthermore, gene panel NGS of BM36 tumor tissue and short-term cultures revealed a Janus kinase 3 (JAK3) somatic variant (V718L)." (PMID 38985431, 2024). "Furthermore, it was shown that the mutant JAK3 protein promoted PD-L1 expression in vitro and PD-L1 positivity is substantially enriched in clinical tumor samples with JAK3 mutations." (PMID 29082853, 2017). "Therefore, TYK2 and JAK3 may function as biomarkers in stomach cancer, as they are associated with tumor aggressiveness and metastasis." (PMID 34439323, 2021). "To further investigate the impact of Stigmasterol and JAK3 expression on the tumor formation ability of BCSCs in vivo, we first established the JAK3 stably overexpressed BCSCs (4T1 sorted BCSCs)." (PMID 39991585, 2025). "To find more evidence supporting the positive regulation of miR155HG on JAK3 mRNA levels, we also used several publicly available datasets as well as RT-qPCR of miR155HG and JAK3 mRNA levels in tumor tissues from HCC patients." (PMID 40486832, 2025). "In contrast, those in the JAK3 overexpressed group formed 2.3 cm diameter tumors, suggesting JAK3 promotes the tumor formation ability of BCSCs in vivo." (PMID 39991585, 2025). "More importantly, it was evidenced that Stigmasterol inhibited JAK3 expression in tumor tissues, and the inhibitory effect of Stigmasterol on tumor formation was partially reversed by JAK3 expression." (PMID 39991585, 2025). "Attenuation of JAK2 by miR-204 in HNSCC inhibited the JAK2/JAK3 pathway preventing tumor angiogenesis and increased sensitivity to cetuximab suggesting a tumor suppressive activity." (PMID 40176914, 2025).
tumor (continued). "Further validation found decreased methylation and elevated expression of JAK3 in the F. nucleatum-treated LSCC cell group; F. nucleatum abundance and JAK3 gene expression had a positive correlation in tumour tissues." (PMID 38536233, 2024). "It is reported that in JAK3 mutation or NOTCH1-induced T-ALL, PHF6 deletion can significantly accelerate the development of the disease, indicating that PHF6 plays a tumor-inhibitory role in T-ALL." (PMID 38336746, 2024). "JAK3 is a member of the tyrosine kinase family with importance in cytokine signaling and plays a significant role in BC tumor cell invasion and transendothelial migration as well as an effector of a JAK3-distinct immune cell response." (PMID 39696035, 2024). "JAK3-V722I was found in several tumor types 22, 23 and reported both as somatic as well as germline mutation." (PMID 38244120, 2024). "Comparison of zebrafish prkdc, rag2 and jak3 mutant models has revealed the prkdc mutants as the most efficient platform for tumor xenotransplantation." (PMID 37047441, 2023). "JAKs families are tightly connected to the development in a variety of tumors and non-tumor diseases, among them, JAK3 is an essential regulatory gene, and its mediated signaling pathway keep highly active in these diseases." (PMID 38095643, 2023). "We identified IL2RG as a target enriched in classical tumor epithelium and has previously shown to attenuate PanIN growth through JAK3 suppression in orthogonally implanted pancreatic cancer." (PMID 37633924, 2023). "The selective JAK3 inhibitor has recently been demonstrated to have a potent anti-tumor activity in pre-clinical study." (PMID 37486391, 2023). "In the colon, tumor growth is significantly influenced by the relative balance between proliferation and apoptosis; Jak3 plays an important role in keeping the balance between proliferation and apoptosis." (PMID 33814980, 2021). "A recent study demonstrated that 3-deazaneplanocin A, an EZH2 inhibitor, was shown to suppress NK tumor cell growth and increase the apoptosis of these cells and treatment with a JAK3 inhibitor such as tofacitinib enhanced H3K27me3 in ENKTL tumor cell lines." (PMID 32098335, 2020). "The mutation allele frequencies of ATM and JAK3 were significantly correlated with the disease stage, and mutated KMT2D, ASXL3 and JAK3 were positively correlated with the metabolic tumor burden of the patients." (PMID 32695399, 2020). "As expected, RNA-Seq expression data in tumour 238 showed a significant increase in the levels of expression of the fusion transcript with respect to JAK3 alone." (PMID 30914738, 2019). "A selective inhibitor of JAK3 (PRN371) has recently been demonstrated to have more potent anti-tumor activity than Tofacitinib in a xenograft model of ENKTL with a JAK3 mutation." (PMID 29966370, 2018). "Overall, our findings of the anti-proliferative effects of miR-218 in lung adenocarcinima cells, through the direct targeting of IL-6R and JAK3, further corroborate a tumor suppressive role for miR-218 in NSCLC." (PMID 28830450, 2017). "On the basis of the microarray data, we chose to focus on MCL-1 and JAK3 genes which appeared downregulated in tumor-reactive CD8+ T cells from RCC patient." (PMID 27063186, 2016). "Overall, this is the first study, which demonstrates that N225K and A550V PTPN6 mutations cause loss-of-function leading to JAK3 mediated deregulation of STAT3 pathway and uncovers a mechanism that tumor cells can use to control PTPN6 substrate specificity." (PMID 26565811, 2015). "Our work provides evidence that aberrant Jak3/STAT activation represses a novel tumor suppressor miRNA in CTCL." (PMID 26244872, 2015).
tumor (continued). "In conclusion, we provide the first evidence that de-regulated Jak3/STAT3/STAT5 signalling in CTCL cells represses the expression of the gene encoding miR-22, a novel tumor suppressor miRNA." (PMID 26244872, 2015). "Studies showed that tumor condition suppressed expression of JAK3 and tyrosine phosphorylation of STAT5." (PMID 24053127, 2013). "BLNK is a tumor suppressor that regulates IL-7-dependent survival of pre-B cells via direct inhibition of JAK3, indicating a crucial role of JAK3 in pre-B cell proliferation." (PMID 20149240, 2010). "Given that HPV oncoproteins like E7 are known to promote STAT5 activation, we hypothesize that in HPV16+ SCC, ATXN3 may facilitate tumor progression through the JAK3/STAT5 pathway." (PMID 41507147, 2026). "This study highlights the important role of HCC‐derived exosomal miR‐500a‐3p in intercellular communication, which may be responsible for HSC activation and tumor aggressiveness via the downstream SOCS2/JAK3/STAT5A/STAT5B regulatory loop." (PMID 39574357, 2025). "Early studies have shown that several pro-angiogenic mechanisms—including the VEGF/VEGFR axis, the CXCR4/CXCL12 chemokine pair, and the JAK3/STAT5 signaling pathway—promote tumor cell proliferation, homing, survival, and dissemination through autocrine feedback loops." (PMID 41171472, 2025). "To delve deeper into the regulatory mechanisms of IFIT3 in malignant tumor progression and immune infiltration, we combined the KEGG results and identified a potential pathway: the JAK3-STAT pathway, which may be associated with IFIT3." (PMID 39139574, 2024). "As the primary necessity to treat GBM patients is to inhibit the tumor cells from proliferating, we treated U87 and U251 cells with the JAK3 inhibitor WHI-P131 to investigate whether it can effectively block their extensive rate of proliferation." (PMID 37947625, 2023). "There were also phenotypically different cells of neuronal origin such as astrocytes in the treated wells, suggesting that the JAK3 inhibitors not only prevented tumor cell proliferation but also induced their differentiation into a more mature stage, in which they were not proliferating." (PMID 37947625, 2023). "In addition, DOK7 overexpression also reduced the levels of p-JAK1, p-JAK2 and p-JAK3 in the tumor tissues." (PMID 38095644, 2023). "Common gene variants could be demonstrated in only two out of the six evaluated cases, each presenting with a single gene variant occurring in both tumor foci (BRAF and JAK3)." (PMID 31963551, 2020). "Furthermore the levels of expression of total JAK3 increases significantly in tumours 554 (FPKM values from 25,19 in controls to 53.80; log2FC = 1.09) and 840 (FPKM values from 22.60 in controls to 68.30; log2FC = 1.5)." (PMID 30914738, 2019). "Notably, RNA-Seq expression in tumour 238 revealed an increase in the relative-levels of expression of the fusion transcript (FPKM value: 133.77) with respect to JAK3 (FPKM value: 105.96)." (PMID 30914738, 2019). "Together, IL‐7 enhanced the anti‐tumour efficacy of cisplatin via JAK3/STAT5 pathway in vivo." (PMID 31599032, 2019). "To directly address miR-29b and miR-198 specificity and MCL-1 and JAK3′s involvement in tumor suppressor activity, we investigated the effect of both miRNAs inhibition on apoptosis, as induction of immune cell apoptosis is a crucial event during malignant transformation." (PMID 27063186, 2016).
tumor (continued). "This study extends the emerging paradigm of JAK3 activating mutations to CTCL and further implicates SOCS1 in the control of lymphomatous signaling, thus widening the number of potentially actionable targets in affected neoplasms." (PMID 27144517, 2016). "On the other hand, coordinate down-regulation of MCL-1 and JAK3 in T cells from RCC patients could represent a mechanism of immune evasion which confers a survival advantage to the tumor in the face of a muted attack by the immune system." (PMID 27063186, 2016). "Since JAK3 kinase specifically interacts with its cognate receptor γc chain, and expression of both molecules is interdependent, we further analyzed, by RT-PCR, JAK3 expression in normal and tumor renal cells." (PMID 22363690, 2012). "We observed that, of the Jak proteins and associated Stat proteins, phosphorylations of Jak-3 and Stat-5 were down regulated in CD4+ T cells by tumor-shed PGE2, which could be ameliorated by pre-treatment of the tumor cells with theaflavins." (PMID 19812686, 2009). "Recent studies have further revealed the involvement of JAK3 in tumors immune evasion and microenvironmental crosstalk, suggesting that JAK3-targeted therapy could not only suppress oncogenic signalling but also restore anti-tumor immunity." (PMID 41385500, 2025). "Notably, F. nucleatum abundance in tumour tissues correlated positively with JAK3 expression." (PMID 38536233, 2024). "Moreover, RNA-Seq analysis of lesional CTCL skin revealed activated signaling pathways in CTCL compared with HD, including NF-κB and JAK/STAT signaling, and highlighted upregulation of JAK3 (P < 0.0001) and NF-κB (P < 0.0001) genes with highest expression in tumor lesions compared with HD." (PMID 37427589, 2023). "JAK3-mediated activation of the transcription factor STAT5 is critical in IL-2–stimulated NK cells in vitro and Jak3 inhibition has been found in NK cells co-cultured with MDSC isolated from the spleen of tumor-bearing mice associated with reduced STAT5 in NK cells." (PMID 31057536, 2019). "Interestingly, the entire phenomena could be reverted back by theaflavins that restore cytokine-dependent IL2Rγc/Jak-3/Stat-5A signaling in CD4+ T cells thereby protecting them from tumor-shed PGE2-induced apoptosis." (PMID 19812686, 2009). "Thus, γc down regulation and inhibition of Jak-3/Stat-5A signaling by PGE2 present in the tumor supernatant, as obtained here, may fail to support sustained Bcl-2 expression, leading to CD4+ T cells susceptibility towards apoptotic death." (PMID 19812686, 2009). "In tumor-infiltrating NK cells derived from HCC patients, the RNA levels of both JAK3 and miR155HG were observed to be downregulated." (PMID 40486832, 2025). "Previous studies have shown that co-alterations of JAK3 and SOCS1 amplify downstream STAT signaling and enhance tumor cell survival." (PMID 41008827, 2025). "We observed that F. nucleatum treatment induced demethylation and upregulation of JAK3, contributing to activation of the PI3K-Akt and JAK-STAT signalling pathway, and potentially participating in tumour metastasis." (PMID 38536233, 2024). "More importantly, we reveal a relevant mechanism that PIK3CD, but not PIK3CA and PIK3CB, is transcriptionally regulated by the pro‐inflammatory IL2/JAK3/STAT5 axis and tumor‐infiltrating immune cells such as lymphocytes." (PMID 38545256, 2024). "The identified epigenetic PARPi hallmarks contained hundreds of DMRs; however, only a few DMRs were reported as tumor driver genes (SOX2, POU2AF1, PTK6, VHL, JAK3, and EZH2) or as HRD genes (RAD51C)." (PMID 38927686, 2024). "In CC cases with heterogeneous EMR1 expression, specific JAK-STAT genes (JAK2, JAK3, STAT1, STAT2, and STAT3) were upregulated in the EMR1-H/L ROI compared to those in the EMR1-N ROI within the same tumor." (PMID 38673975, 2024). "Confirming screen robustness, sgRNAs targeting genes required for T cell function were depleted from the tumor, including Tap1, B2m, CD47, Jak1, and Jak3." (PMID 38099496, 2023).